RN7SKP98 (RN7SK pseudogene 98)
Gene: Miscellaneous RNA gene on chromosome 1 (212,099,521 to 212,099,676, reverse strand). Ensembl gene ENSG00000252879.
Homologues: Orthologues: chimpanzee 7SK (94% identical). Paralogues in human: RN7SKP9 (77% identical), RN7SKP251 (76% identical), RN7SKP37 (76% identical), RN7SKP203 (75% identical), 7SK (74% identical), RN7SKP180 (74% identical), RN7SKP189 (74% identical), RN7SKP25 (74% identical), RN7SKP30 (74% identical), RN7SKP50 (74% identical), RN7SKP80 (74% identical), RN7SKP133 (73% identical), and 284 more.